IL6 (interleukin 6)
Diseases named in the same sentence as IL6 in open-access papers (continued):
Sharing a sentence is not in itself a finding about the gene and the disease.
Sepsis (continued). "Notably, impedance aggregometry findings using collagen as the activator proved to be a better biomarker for both diagnosis of severe sepsis in critical illness and survival of severe sepsis than procalcitonin, interleukin 6, C-reactive protein and platelet count." (PMID 23088388, 2012). "A potential explanation could be that patients who have higher IL-6 concentrations but did not meet clinical criteria for severe sepsis had more severe disease and therefore associated with higher mortality." (PMID 21853050, 2011). "As we found that the serum levels of IL-6 were significantly higher in WT mice than in plg-/- mice 24 h after induction of sepsis, we tested the hypothesis that neutralization of IL-6 may delay the onset of death, or improve the survival rate in our sepsis model." (PMID 21931850, 2011). "The role of IL-6 in sepsis may be as a parameter of disease severity." (PMID 21939530, 2011). "In addition, during sepsis, since the IL-6 levels are highest in WT mice, intermediate in plg+/- mice, and lowest in both tPA-/-/uPA-/- and plg-/- mice, the increase in cytokine levels appears to be related not only to levels of plasminogen but also to levels of active plasmin." (PMID 21931850, 2011). "IL-6 is the second best after PCT but the sharp decline of IL-6 levels after admission in patients with sepsis suggests that late sampling may easily cause false negative results." (PMID 21687569, 2011). "Of note, this association could not be observed for IL-6, although IL-6 serum levels were strongly increased in sepsis patients." (PMID 21281508, 2011). "Furthermore, comparison of thromboelastometry findings with the conventional biomarkers procalcitonin, interleukin 6, and C-reactive protein demonstrates a superior accuracy of the thromboelastometry lysis index in identifying patients with severe sepsis in critically ill patients." (PMID 20929576, 2010). "Furthermore u-PA is potently upregulated by the proinflammatory cytokines TNF-α and IL-6 in a variety of human cancer cell lines in vitro and the u-PA system is significantly activated by infection and sepsis in vivo as evidenced by increased circulating levels of u-PA." (PMID 17242699, 2007). "Sleep interruption also increased the levels of serum cytokines (including IL-23 before sepsis was induced, and IL-6, TNF-α, MCP-1, and IL-10 after sepsis), and amplified macrophage cytokine production ex vivo." (PMID 42257268, 2026). "Cardiac impairment in patients with sepsis involves cytokines (e.g., TNF-α and IL-6) that disrupt calcium homeostasis, mitochondrial function, and contractility while inducing nitric oxide overproduction, which reduces myocardial responsiveness." (PMID 41521316, 2026). "Inflammatory mediators were markedly increased in sepsis (TNF-α, IL-6, HMGB1, TLR-4, and NF-κB; all p < 0.001 vs. Control) and significantly downregulated by pioglitazone (p < 0.01, p < 0.001, p < 0.001, p < 0.01, p < 0.01 vs. CLP + Saline, respectively)." (PMID 41899201, 2026). "Pro‐inflammatory IL‐1β, IL‐6, IL‐8, IL‐12/23p40, TNF‐α, and IFN‐γ, and anti‐inflammatory (regulatory) cytokine IL‐10 play key roles in the acute phase of sepsis." (PMID 41474380, 2026). "Activation of membrane-bound TREM-1 promoted proinflammatory signaling, inducing cytokines such as interleukin 6 (IL-6), TNF-α, and IL-8, as demonstrated in models of sepsis and inflammatory bowel disease." (PMID 41273150, 2026). "This process triggers the release of IL-6, IL-1β, and TNF-α, which drive systemic inflammation, sepsis, septic shock, and disseminated intravascular coagulation (DIC)." (PMID 41521316, 2026). "The treatment significantly reduced serum levels of key biomarkers of sepsis, including C-reactive protein (CRP), lactate (Lac), tumor necrosis factor-alpha (TNF-α) and interleukin-6 (IL-6), and dose-dependently improved the survival of septic mice." (PMID 41157235, 2025).
Sepsis (continued). "Uncontrolled inflammation in sepsis results in an increase in the release of pro-inflammatory cytokines, including tumor necrosis factor alpha (TNF-α), interleukin-1 beta (IL1-β), IL-6, and HMGB-1." (PMID 39838305, 2025). "Anti-inflammatory agents, such as IL-6 and TNF-α inhibitors, have shown potential in mitigating inflammation in both sepsis and cancer, though their dual roles in protective and pathological processes require careful consideration." (PMID 40563999, 2025). "In sepsis, procalcitonin is released by various cells and tissues, including the liver, and, like CRP, its production is induced by IL-6, alongside other inflammatory cytokines and lipopolysaccharide." (PMID 41007672, 2025). "XBJ exerted therapeutic effects on sepsis and septic-AKI through suppression IL-1β/MMP9, IL-6/MMP9 and TNFα/MMP9 at both mRNA and protein level." (PMID 41042728, 2025). "Given that multi-organ dysfunction in sepsis is primarily driven by a hyperinflammatory cytokine storm, we examined serum levels of TNF-α, IL-6, and IL-1β and found that ILA effectively mitigated systemic inflammatory response." (PMID 40761792, 2025). "Sepsis-induced hyperinflammation is primarily driven by TNF-α, IL-6, and IL-1β, whose plasma levels negatively correlate with survival in patients." (PMID 41157235, 2025). "We observed that enhancing O-GlcNAcylation of FTO using an OGA inhibitor (TMG) decreased LPS-induced TNF-α/IL-1β/IL-6 inflammation and reduced septic mouse mortality, which may constitute a protective mechanism to limit exacerbated inflammation in acute stress conditions such as LPS-induced sepsis." (PMID 40642069, 2025). "The mice displaced well-controlled inflammatory responses, as shown by high levels of interleukin-6 (IL-6) at the early/acute stage of sepsis (3 hours after CLP), with IL-6 levels under control at 24 and 48 hours after CLP." (PMID 40048257, 2025). "Toll-like receptors (TLRs) are commonly activated receptors in sepsis, leading to the activation of NF-κB and the subsequent release of inflammatory factors, such as TNF-α, IL-1β, IL-6, and IL-18." (PMID 41311552, 2025). "One study found that IL-6 and TNF-α levels were significantly higher in EOS compared to late-onset sepsis, particularly within the first 48 h of life, reinforcing their value for early diagnosis." (PMID 40806937, 2025). "In contrast to the LPS-treated mice, the expressions of the TNFα and IL6 mRNAs were markedly lower in the T0+LPS-treated group, suggesting that LXR protects against sepsis-induced lung injury." (PMID 40994643, 2025). "To confirm this, we used an NAMPT inhibitor, FK866, in this sepsis model and observed that FK866 significantly attenuated kidney injury and IL-6 production induced by LPS and CD38 ligation." (PMID 39568061, 2025). "A previous report, using LPS administration as a sepsis model, demonstrated that CD38 promotes the expression of proinflammatory cytokines, including IL-1β, IL-6, and IL-12." (PMID 41488275, 2025). "Adhesion burden, neutrophil-rich infiltration, fibrosis, and neovascularization were all heightened with sepsis and were consistently attenuated by NAC, while circulating IL-6 and TNF-α fell below control levels under NAC exposure." (PMID 41440550, 2025). "A prior study showed significant reductions in plasma IL-6 and TNF-α levels in rats following sepsis induction with Androstenediol administration." (PMID 39955435, 2025). "Since proinflammatory cytokine overproduction is indicative of sepsis, we evaluated the levels of TNF‐α, IFN‐γ, IL‐1α, IL‐1ß, IL‐6, IL‐10, IFN‐ß, IL‐17A, IL‐23, IL‐27, MCP‐1, IL‐12p70, and GM‐CSF in the serum at 16 h after LPS‐induced septic shock." (PMID 39482884, 2025). "lncRNA H19 alleviates sepsis-induced acute lung injury by downregulating the expression of TNF-α, IL-6, IL-17, caspase-3, caspase-9, and Bax while upregulating Bcl-2 levels, thereby suppressing lung cell apoptosis and inflammation." (PMID 39940682, 2025).
Sepsis (continued). "Sepsis can disrupt the BBB, resulting in an elevation of inflammatory factors within the brain, such as interleukin-6 (IL-6) and high mobility group box 1 (HMGB1)." (PMID 41357214, 2025). "These elevated eCIRP levels, observed in the context of these inflammatory diseases, induce macrophage production of TNF-α, IL-1β, and IL-6, contributing to multi-organ dysfunction, including ALI and acute kidney injury (AKI) in sepsis." (PMID 40332009, 2025). "The cytokine storm is a dangerous hyperinflammatory state associated with elevated levels of several pro-inflammatory cytokines (IL-1β, IL-2, IL-6, IL-17, IL-8, TNF-α) and chemokine L2 (CCL2) and it is an integral part of sepsis." (PMID 40650213, 2025). "Compared with the Sepsis group, the Cur + Sep group showed significantly lower Paller damage scores, reduced Scr, BUN, TNF‐α, IL‐1β, IL‐6, MDA, Fe2+ levels, and ACSL4 protein expression (all p < 0.05)." (PMID 41140036, 2025). "Hyperactivation of the immune system during sepsis leads to the massive release of pro-inflammatory cytokines such as tumor necrosis factor- α (TNF- α), interleukin-6 (IL-6), and interleukin-1 β (IL-1 β)." (PMID 40276499, 2025). "Nicotine suppresses the innate and adaptive immune response by reducing the secretion of pro-inflammatory cytokines (IL-1, IL-6, TNF-α), which reduces the activity of lymphocytes and decreases the possibility of cytokine storm and sepsis." (PMID 40650213, 2025). "This systemic inflammation is prevalent in sepsis, and is characterized by elevated inflammatory markers such as C-reactive protein (CRP), tumor necrosis factor-alpha (TNF-α), and interleukin-6 (IL-6)." (PMID 40098009, 2025). "Cytokines known to activate the adaptive immune system were generally higher in sepsis compared to the healthy cohort, including RANTES (p=0.01), G-CSF (p<0.0001), M-CSF (p<0.0001), IL-6 (p<0.0001), IL-8 (p<0.0001), IL-27 (p<0.0001), and MIP-1β (p<0.0001)." (PMID 39935482, 2025). "Serum markers such as procalcitonin (PCT), interleukin-6 (IL-6), C-reactive protein (CRP), and cystatin C have been widely studied in the context of sepsis and kidney injury." (PMID 41281283, 2025). "The prognostic significance of HBP, IL-6, PCT, CRP, Lac, and SOFA for patients diagnosed with severe pneumonia and sepsis." (PMID 41293058, 2025). "Current interest lies in the overexpression of cytokines such as IL-6, IL-10, and CCL2 due to their reported correlation with sepsis severity." (PMID 40178612, 2025). "Unsurprisingly, serum cytokines (TNF-α, IL-6, and IL-10) in probiotic-treated CLP sepsis mice were lower than in the untreated CLP group." (PMID 41444762, 2025). "Serum levels of IL-6, TNF-α, IL-1β, and HMGB1 were markedly elevated in sepsis groups compared to Sham (P < 0.001)." (PMID 41281995, 2025). "Studies have demonstrated that C-reactive protein, procalcitonin, tumor necrosis factor α, interleukin-6, and neutrophil surface receptors (CD64) are currently widely utilized as biomarkers for monitoring sepsis." (PMID 40867545, 2025). "Statistical analysis was performed on serum concentrations of CRP, IL-6, IL-1β, TNF-α, IL-10, and PDL1 from healthy individuals and sepsis patients, using a 95% CI." (PMID 40568710, 2025). "Studies in sepsis animal models have shown that reducing ADAM17 expression decreases serum levels of IL-1β, IL-6, and TNF-α while also decreasing ICAM-1 and VCAM-1 expression in lung and liver tissues, thereby significantly improving 72-h survival in mice." (PMID 41280722, 2025). "High-dose levosimendan significantly reduced TNF-α, IL-1β, IL-6, and MCP-1 levels by the 10th hour, accompanied by improved Murine Sepsis Scores." (PMID 40566580, 2025). "During the initial inflammatory phase of sepsis, M1 macrophages release cytokines such as tumor necrosis factor-alpha (TNF-α) and interleukin-6 (IL-6), intensifying lung injury." (PMID 39910395, 2025).
Sepsis (continued). "The central role of cytokines like IL-6 and TNF-α in both sepsis and cancer has led to the development of targeted therapies aimed at modulating their activity." (PMID 40563999, 2025). "The findings revealed a significant elevation in the levels of interleukin-1β (IL-1β), interleukin-6 (IL-6), and tumor necrosis factor-α (TNF-α) in both BALF and serum of sepsis-induced ALI mice." (PMID 41496909, 2025). "It has been previously shown that Sirt1 is downregulated in macrophages in preclinical models of sepsis and may play a role in orchestrating innate immune activation, particularly through the activation of NF-κB and the subsequent production of pro-inflammatory cytokines such as IL-6 and TNF-α." (PMID 41096578, 2025). "Nominally pro- (IL-6, MIP-2, TNFα) and anti-inflammatory cytokines (IL-10) form a double-edged sword in sepsis and septic shock and are required to respond to, and eliminate infection, while excessive production causes organ damage." (PMID 41155249, 2025). "Further analysis demonstrated that SFT2D1 inhibition significantly decreased the expression levels of key inflammatory cytokines CXCL10 and IL-6 (P < 0.05), suggesting a role for SFT2D1 in promoting the inflammatory response in sepsis." (PMID 40370519, 2025). "The pathogenesis of sepsis and cytokine storm involves the excessive release of cytokines, including tumor necrosis factor-α (TNF-α), interleukin-1 (IL-1), interleukin-6 (IL-6), and interferon-γ." (PMID 41010563, 2025). "Sepsis also triggers an SIRS, marked by the release of proinflammatory cytokines such as IL-6 and tumor necrosis factor-alpha." (PMID 40546531, 2025). "Compared to the sham group, the levels of IL-6, IL-1β, IL-10 and TGF-β in the sepsis group and the placebo group were also significantly elevated (p < 0.01)." (PMID 41584453, 2025). "Compared with control mice, these mice presented decreased levels of proinflammatory cytokines, such as IL-1β, IL-6, and TNF-α; reduced sepsis-induced organ injury; and improved survival." (PMID 39675717, 2025). "In a mouse sepsis model, disulfide effectively reduced mortality and decreased the levels of inflammatory cytokines such as IL-1β, TNF, and IL-6 in serum." (PMID 41041277, 2025). "Circulating EVs notably exacerbate the inflammatory response to sepsis in both serum and lung tissue by enhancing the production of proinflammatory factors such as tumor necrosis factor-α (TNF-α), interleukin-6 (IL-6), and interleukin-1β (IL-1β)." (PMID 39967672, 2025). "Previous studies have shown that elevated interleukin-6 levels, among other proinflammatory cytokines, directly correlate with decreased ADAMTS13 activity in patients with sepsis." (PMID 40725629, 2025). "A clinical study using patient serum samples reveals reduced GPX4 expression correlating inversely with proinflammatory markers such as IL-6 and TNF-α, with GPX4 levels predicting sepsis severity in pediatric cohorts (SOFA score > 10)." (PMID 41250137, 2025). "When used together, IL-6 and CRP demonstrated 67% sensitivity and 62% specificity in predicting sepsis." (PMID 41011807, 2025). "This study focused on patients with severe pneumonia-induced sepsis to investigate the roles of serum HBP and IL-6, along with traditional indicators." (PMID 41293058, 2025). "Severe leptospirosis develops a cytokine storm characterized by high levels of IL-6, TNF-α, and IL-10, resembling sepsis-like phenotypes." (PMID 41445751, 2025). "In sepsis, inflammatory mediators such as TNF-α and IL-6 enhance TF expression on endothelial cells, promoting thrombosis." (PMID 40226813, 2025). "During the early phases of sepsis, pro-inflammatory cytokines such as tumor necrosis factor-alpha (TNF-α), interleukin-1β (IL-1β), and interleukin-6 (IL-6) are released, initiating the inflammatory cascade." (PMID 40566580, 2025). "Dexmedetomidine can reduce the levels of IL-6 and TNF-αin patients with sepsis, while also decreasing in-hospital mortality and 28-day mortality." (PMID 41195185, 2025).
Sepsis (continued). "Recent research confirms the significance of biomarkers such NLR, IL-6, CRP, procalcitonin, and lactate levels in diagnosing and monitoring sepsis, systemic infection, and SIRS." (PMID 40870412, 2025). "Macrophages are recruited during sepsis, and release various inflammatory factors such as TNF, IL-1β and IL-6, along with chemokines like CCL6 and CD14, and the transcription factor NF-κB1." (PMID 40775729, 2025). "By combining RDW and APACHE II score with PCT, IL-6, CRP, and cystatin C, clinicians can obtain a more comprehensive understanding of both the inflammatory and renal aspects of sepsis." (PMID 41281283, 2025). "Supporting these findings, IFN-gamma deficient mice showed a 50% reduction in susceptibility to sepsis, a lower plasmatic concentration of NETs, IL-6, and reduced frequency of CXR4+ PD-L1+ neutrophil compared to WT mice under CLP-sepsis." (PMID 40241761, 2025). "At the same time, during the development of sepsis, the expressions of JAK2 and STAT3 proteins were significantly up-regulated, and the transcription and expression of downstream inflammatory factors IL-6 and TNF-α were also increased." (PMID 40338919, 2025). "THCQ reduces key inflammatory factors in sepsis, such as TNF-α, IL-1β, and IL-6, inhibits oxidative stress, and alleviates iron overload, indicating its multiple protective mechanisms in mitigating the inflammatory cascade of sepsis." (PMID 40963685, 2025). "Accumulating evidence demonstrates that blockade of inflammatory cascades effectively mitigates sepsis-induced cardiomyocyte pyroptosis, including inhibition of TNF, IL-1, IL-6, IL-7, IL-15, coagulation factors, and complement C5a." (PMID 41256846, 2025). "This meta-analysis demonstrated that ulinastatin significantly reduces mortality and inflammatory markers such as CRP, IL-1β, IL-6, IL-8, IL-10, PCT, and TNF-α in patients with sepsis compared to control group." (PMID 40667510, 2025). "In this case, coagulopathy, high IL-6, and liver failure reflected the difficulty of reversing DIC in fulminant, toxin-driven sepsis." (PMID 40564724, 2025). "The survival curve analysis revealed that sepsis patients with elevated serum levels of ACSL4, CL-11, and IL-6 above the respective cutoff values had significantly shorter survival times." (PMID 40264754, 2025). "These cytokines play a crucial role in sepsis, with IL-1β and TNF-α being pro-inflammatory factors that exacerbate systemic inflammation, while IL-6 is closely involved in the acute-phase response and immune modulation." (PMID 40422869, 2025). "Notably, patients presenting with IL-6 ≥ 2000 pg mL−1 enjoyed a 17% absolute survival gain—echoing the biologic heterogeneity emphasised in recent precision-sepsis frameworks and suggesting that inflammatory-load enrichment may be essential to demonstrate benefit in future trials." (PMID 40868084, 2025). "Liver injury in sepsis often involves complex pathological mechanisms, including cytokine storms (e.g., TNF-α, IL-6), microcirculatory disturbances, endotoxin assault, and cholestasis." (PMID 41378216, 2025). "To characterize the anti-inflammatory effect of DTP against LPS-induced sepsis, we quantified the concentrations of the inflammatory markers TNF-α, IL-6, and IL-1β in mouse serum by ELISA." (PMID 41009021, 2025). "Many proinflammatory cytokines, such as IL-1, IL-6, IL-8, IL-12, IL-18, TNF-a, and IFN-r, are highly expressed, leading to cytokine storms after sepsis develops." (PMID 40136690, 2025). "This meta-analysis demonstrated that dexmedetomidine exerts a positive effect on reducing interleukin-6 (IL-6) and tumor necrosis factor-α (TNF-α) levels in patients with sepsis, as well as lowering in-hospital mortality and 28-day mortality." (PMID 41195185, 2025). "The elevated expression of Il6 mRNA in the renal stromal cells and increased NAMPT expression in CD38-positive macrophages represent novel findings in both mice and humans with sepsis." (PMID 39568061, 2025).